RAB40B (RAB40B, member RAS oncogene family)
Description:
RAB40B small GTPase acts as substrate-recognition components of the ECS(RAB40B) E3 ubiquitin ligase complex which mediates the ubiquitination of target proteins. The Rab40 subfamily belongs to the Rab family that are key regulators of intracellular membrane trafficking, from the formation of transport vesicles to their fusion with membranes. Rabs cycle between an inactive GDP-bound form and an active GTP-bound form that is able to recruit to membranes different sets of downstream effectors directly responsible for vesicle formation, movement, tethering and fusion. As part of the ECS(RAB40B) complex, GTP-bound RAB40B promotes LIMA1/EPLIN ubiquitination and degradation, thereby regulating leading-edge actin dynamics during cell migration. As part of the ECS(RAB40B) complex, GTP-bound RAB40B also ubiquitinates RAP2A GTPase which promotes its localization to lamellipodia and activation to drive cell migration. The ECS(RAB40B) complex does not mediate canonical ubiquitin-dependent degradation of RAP2. RAB40B also binds TKS5/SH3PXD2A effector independently from ECS complex to promote invadopodia-mediated extracellular matrix degradation.
Synonyms: SEC4L; RAR
Tractability: Antibody: UniProt places it where antibodies can reach, with high confidence; its Gene Ontology location is reachable by antibodies, with medium confidence. PROTAC: ubiquitination databases record sites on it.
Gene: Protein-coding gene on chromosome 17 (82,654,973 to 82,698,698, reverse strand). Ensembl gene ENSG00000141542.
Subcellular location: Cell membrane; Cytoplasm, cytosol; Cell projection, lamellipodium membrane; Cell projection, ruffle
Subcellular location (Human Protein Atlas): Vesicles
Pathways (Reactome):
Metabolism of proteins: RAB geranylgeranylation
Gene Ontology:
Molecular function: protein binding; ubiquitin-like ligase-substrate adaptor activity; GTPase activity; G protein activity; GTP binding
Biological process: cellular detoxification; negative regulation of actin filament bundle assembly; positive regulation of cell migration; proteasome-mediated ubiquitin-dependent protein catabolic process; protein ubiquitination; regulation of lamellipodium organization; exocytosis; intracellular signal transduction
Cellular component: cytosol; lamellipodium; lamellipodium membrane; nuclear envelope; perinuclear region of cytoplasm; ruffle; endosome; plasma membrane; synaptic vesicle
Genetic constraint (gnomAD): Loss-of-function variants: 20 observed, 18.5 expected, observed/expected ratio (o/e) 1.08, 90% interval 0.76 to 1.57. The upper end of that interval is the gene's LOEUF score, 1.57, which puts it in group 6 of 6, group 1 being the genes least tolerant of losing a copy. Missense variants: 329 observed, 342.14 expected, observed/expected ratio (o/e) 0.96, 90% interval 0.88 to 1.05. Synonymous variants: 159 observed, 145.17 expected, observed/expected ratio (o/e) 1.1, 90% interval 0.96 to 1.25.
Homologues: Orthologues: chimpanzee RAB40B (100% identical), macaque RAB40B (99% identical), dog RAB40B (95% identical), guinea pig RAB40B (95% identical), rabbit RAB40B (94% identical), mouse Rab40b (93% identical), tropical clawed frog rab40b (88% identical), zebrafish rab40b (84% identical), rat Rab40b (81% identical), pig RAB40B (73% identical). Paralogues in human: RAB40AL (88% identical), RAB40A (88% identical), RAB40C (80% identical), RAB10 (29% identical), RAB8A (29% identical), RAB1A (28% identical), RAB1B (28% identical), RAB8B (28% identical), RAB13 (28% identical), RAB15 (28% identical), RAB6A (28% identical), RAB3B (27% identical), and 56 more.
Diseases named in the same sentence as RAB40B in open-access papers:
RAB40B is named in the same sentence as 10 diseases in open-access papers, as found by Europe PMC text mining. Sharing a sentence is not in itself a finding about the gene and the disease. The quoted sentences say what the papers report.
breast carcinoma (5 papers, 2015 to 2024). "Here, we demonstrate that preventing Rab40b–Cullin5 binding increases total cellular EPLIN levels in breast cancer cells and causes its redistribution to stress fibers and the leading edge of migratory lamellipodia." (PMID 33999101, 2021). "We show that in breast cancer cells Rab40b does bind to the CRL5 E3 ligase complex containing Cullin5, Elongin B, Elongin C, and Rbx2 and that mutations to the Rab40b–SOCS box are sufficient to disrupt this interaction." (PMID 33999101, 2021). "Among these, 11 CNVRs overlapped with 12 genes (GSTM2, RAB40B, HLA_DRB5, HLA_DRB6, EYA1, DOCK3, ANKS1B, CACNA1C, RAB11FIP3, BAGE, SGCZ, POM121c) and were specifically associated with breast cancer risk and OS." (PMID 29116104, 2017). "Given that miR-204 decreases cellular levels of Rab40b in breast cancer cells, miR-204 would also be expected to inhibit MMP2 and MMP9 targeting to the forming invadopodia." (PMID 27789576, 2016). "Next, we used publicly available microarray data to analyze Rab40b expression in various breast cancers." (PMID 27789576, 2016). "Highlighted Article: Rab40b plays a key role in mediating invadopodia function during breast cancer cell invasion by binding to Tks5 and functioning as a tether mediating MMP2 and MMP9 targeting to the extending invadopodia." (PMID 27789576, 2016). "Here, we report that Rab40b plays a key role in mediating invadopodia function during breast cancer cell invasion." (PMID 27789576, 2016). "Here, we show that Rab40b is required for breast tumor growth and metastasis in vivo and that Rab40b levels are increased in metastatic breast cancers." (PMID 27789576, 2016). "Taken together, this study describes and characterizes a new Rab40b–Tks5-dependent transport pathway that mediates invadopodia extension and function during breast cancer metastasis." (PMID 27789576, 2016). "Taken together, these data are consistent with the involvement of Rab40b during breast cancer cell invasion." (PMID 27789576, 2016). "Given that Rab40b and Tks5 are upregulated in metastatic breast cancer cells, we also investigated the regulation of Rab40b expression." (PMID 27789576, 2016). "Thus, if Rab40b mediates breast cancer metastasis, Rab40b would be expected to be upregulated in breast tumors." (PMID 27789576, 2016). "Thus, our in vivo studies demonstrate that Rab40b promotes tumor metastasis by regulating primary tumor growth as well as invasion of breast cancer cells." (PMID 27789576, 2016). "Although our findings demonstrate that Rab40b mediates breast cancer invasion it remains unclear how the expression of Rab40b is controlled." (PMID 27789576, 2016). "Importantly, we discovered that Rab40b mRNA expression was increased in basal breast cancer as well as advanced stages of all breast cancer subtypes." (PMID 27789576, 2016). "RAB40B is also a member of the RAS family of oncogenes and plays an important role in breast cancer cell formation, invasion, and metastasis." (PMID 39376611, 2024). "Work from our laboratory specifically identified Rab40b as an important regulator of MMP2/9 secretion and ECM remodeling during breast cancer cell invasion." (PMID 33999101, 2021). "Our recent work identified Rab40b GTPase as a protein required for MMP2 and MMP9 secretion from the invadopodia in breast cancer cells." (PMID 27789576, 2016). "Overall, they identified Rab40b GTPase as the key regulator in MMP-2 and MMP-9 transport and targeting to the plasma membrane in the breast cancer invasion process." (PMID 25629807, 2015). "Consistent with this hypothesis, we demonstrate that Rab40b binds to Cullin5 in a SOCS box–dependent fashion and that formation of this CRL5 complex is required for chemotactic migration and breast cancer cell invasion." (PMID 33999101, 2021). "Rab40b is upregulated in grade 3 breast cancers, but its close homologues Rab40a and Rab40c are not." (PMID 27789576, 2016).
breast carcinoma (continued). "It is still unclear whether Rab40b also regulates MMP2 and MMP9 targeting in other cancers or whether it is limited to breast cancer." (PMID 27789576, 2016). "Thus far, our data have established that Rab40b is required for MMP2 and MMP9 targeting to the invadopodia and for breast cancer metastasis in vitro and in vivo." (PMID 27789576, 2016).
breast tumor (1 paper, 2016). "To test this hypothesis, we analyzed Rab40b expression using publicly available patient breast tumor expression data (NCBI GEO dataset GSE58212)." (PMID 27789576, 2016). "Given that our initial studies suggested that Rab40b is required for MDA-MB-231 cell invasion in vitro, we hypothesized that Rab40b knockdown should also affect breast tumor metastasis in vivo." (PMID 27789576, 2016). "As a whole, our data firmly establish Rab40b as a major regulator of targeted MMP2 and MMP9 secretion and breast tumor growth and metastasis in vivo and in vitro." (PMID 27789576, 2016).
gastric cancer (1 paper, 2023). A primary or metastatic malignant neoplasm involving the stomach. "Finally, study of Rab40B in patients with hepatocellular carcinoma and gastric cancer has shown that Rab40B expression is correlated with poor patient prognosis and cancer metastasis." (PMID 37736498, 2023).
lung carcinoma (1 paper, 2021). "As for other clusters, RAB40B and SLC9A3R2 have been shown to be associated with T/NK cells in the lymph node metastasis of lung cancer." (PMID 34575089, 2021).
metastatic cancers (1 paper, 2016). A carcinoma which has spread from the original site of growth to another anatomic site. "However, it is unclear how cellular levels of Rab40b are regulated and why Rab40b expression is increased in metastatic cancers." (PMID 27789576, 2016).
triple-negative breast carcinoma (1 paper, 2021). An invasive breast carcinoma which is negative for expression of estrogen receptor (ER), progesterone receptor (PR), and human epidermal growth factor receptor 2 (HER2). "Due to the lack of reliable commercial antibodies for Rab40b, we used a previously generated triple-negative breast cancer cell line MDA-MB-231 that stably expresses FLAG-Rab40b." (PMID 33999101, 2021).
cancer (8 papers, 2010 to 2025). A tumor composed of atypical neoplastic, often pleomorphic cells that invade other tissues. "A previous report has suggested that TKs5 interacts with Rab40b or Nck1 to regulate the initiation and maturation of invadopodia, structures crucial for cancer cell invasion and metastasis." (PMID 40575485, 2025). "Coexpression of TKs5 and Rab40b in B16-F10 cancer cells reversed p17-modulated suppression of the formation of invadopodia." (PMID 39066315, 2024). "In non-small cell lung carcinoma samples, Rab40B was shown to be overexpressed specifically in areas of cancer cell invasion and metastasis." (PMID 37736498, 2023). "Twist, vimentin, fascin, Mad, Brk, Tsk5, Rab40B, ERK1/2 and PLCγ are associated with bulk cancer cell migration." (PMID 29976164, 2018). "Consistent with the proposed role of Rab40b in regulating cancer metastasis, Rab40b depletion decreased the number of these invasive strands." (PMID 27789576, 2016). "Taken together, our data suggest that Rab40b decreases tumor growth and metastasis, potentially as a direct result of cancer cell invasion as well as effects on primary tumor angiogenesis." (PMID 27789576, 2016). "Consistent with the involvement of Rab40b in cancer cell metastasis, our results show a significantly smaller number of micro-metastases in Rab40b KD lungs compared to control." (PMID 27789576, 2016). "Study of these cancer cell lines has shown that Rab40B overexpression is sufficient to increase cell proliferation, invasion, and migration, suggesting that Rab40B plays an important role in regulating cancer cell metastasis." (PMID 37736498, 2023). "Thus, to further define the role of Rab40b in mediating cancer cell invasion through the ECM, we used three-dimensional (3D) invasion assays, which more closely simulate the in vivo environment." (PMID 27789576, 2016). "We also demonstrated that Rab40b is required for cancer cell invasion in vitro." (PMID 27789576, 2016). "Similarly to Rab40B, Rab40C expression has been analyzed in a variety of cancer types." (PMID 37736498, 2023). "Therefore, in Rab40b KD mice, the inability of the cell to make invadopodia and degrade its surrounding environment could be affecting the movement of cancer cells within the tumor, resulting in smaller tumor size." (PMID 27789576, 2016). "Given that ubiquitin-dependent protein degradation has emerged as an important modulator of invadopodia and cancer metastasis, the identification of Rab40b-SOCS-interacting proteins might shed more light on the mechanisms that regulate MMP2 and MMP9 targeting during cancer cell invasion." (PMID 27789576, 2016). "Even though it has been demonstrated that p17 modulates suppression of TKs5, NCK1, Rab40b, and MMP9 and reduces complex formation of FAK/Src and TKs5/NCK1 in B16-F10 cancer cells, the impact of p17 on the formation of invadopodia is not yet clear." (PMID 39066315, 2024). "This is the first study that identifies a new Rab40b–Tks5- and miR-204-dependent invadopodia transport pathway that regulates MMP2 and MMP9 secretion, and extracellular matrix remodeling during cancer progression." (PMID 27789576, 2016). "Previous reports suggested that the Rab40b-TKs5 complex is a critical regulator of invadopodia formation and function, facilitating the targeted delivery of MMPs to promote ECM degradation and cancer cell invasion." (PMID 40575485, 2025). "Given that it remains unclear how miR-204 affects the cancer invasion machinery, we decided to investigate whether miR-204 inhibits MMP2 and MMP9 targeting to invadopodia by decreasing cellular levels of Rab40b." (PMID 27789576, 2016). "However, how Rab40b regulates targeted MMP2 and MMP9 secretion and localized ECM remodeling remains to be understood, and the machinery that regulates levels of Rab40b in cancer cells is also unknown." (PMID 27789576, 2016).
tumor (3 papers, 2016 to 2021). "In ALDH+CD24-CD44+ BCSCs, we identified P4HA2, PTGR1 and RAB40B as potential prognostic markers, which were virtually related to the status of BCSCs and tumor growth in TNBC cells." (PMID 29471829, 2018). "We demonstrate that miR-204, a known tumor suppressor microRNA, regulates the expression of both Rab40b and Tks5." (PMID 27789576, 2016). "Given that metastasis depends on tumor size as well as time, it is likely that the additional 4 weeks allowed Rab40b-KD tumors to catch up with their control counterparts with respect to metastasis." (PMID 27789576, 2016). "Here, we propose that miR-204 functions as a tumor suppressor by downregulating Rab40b and Tks5 levels, thus directly inhibiting invadopodia extension and localized ECM remodeling." (PMID 27789576, 2016). "In this study, we also analyzed the role of Rab40b in primary tumor metastasis in vivo using a mouse mammary fat pad xenograft model." (PMID 27789576, 2016). "Surprisingly, we also found that Rab40b knockdown resulted in a marked inhibition of primary tumor growth." (PMID 27789576, 2016). "However, in this time-matched study, we were unable to tease apart the direct effect of Rab40b on metastasis given that it also affects primary tumor growth." (PMID 27789576, 2016). "We next sought to explain the decrease in tumor size in Rab40b KD tumors in vivo." (PMID 27789576, 2016). "In order to determine whether Rab40b has any effect on tumor growth and metastasis in vivo, we used SCID mice to perform mammary fat pad injections with either control, KD1 or KD2 MDA-MB-231 cell lines." (PMID 27789576, 2016). "Given that vasculogenesis is vital for tumor growth and progression and MMP2 and MMP9 have been implicated in angiogenesis, we next tested whether Rab40b knockdown is required for primary tumor vascularization." (PMID 27789576, 2016). "Finally, we have shown that cellular levels of both Rab40b and Tks5 are regulated by the known tumor-suppressor microRNA miR-204." (PMID 27789576, 2016). "In order to circumvent the effect of Rab40b on tumor size, we analyzed metastasis in lungs from mice with size-matched large tumors over an extended time and found that there was no noted difference in number of disseminated human cells (Rab40b KD, 31±3.3 cells; control, 20±6.6 cells; mean±s.e.m)." (PMID 27789576, 2016). "Additionally, we show that miR-204 acts as a tumor suppressor by regulating Rab40b and Tks5 expression and consequently inhibiting MMP2 and MMP9 targeting, which leads to a decrease in invadopodia-associated ECM degradation." (PMID 27789576, 2016). "Taken together, our results suggest that Rab40b might regulate vasculogenesis, thus affecting primary tumor growth." (PMID 27789576, 2016). "Importantly, we also demonstrate that Rab40b and Tks5 levels are regulated by known tumor suppressor microRNA miR-204." (PMID 27789576, 2016). "Using both in vitro and in vivo models, we demonstrate that Rab40b and its effector protein Tks5, regulates MMP2 and MMP9 targeting and secretion during cell invasion and tumor growth." (PMID 27789576, 2016). "Furthermore, when tumors were allowed to reach a total tumor burden of 2 cm3 in a size-matched study, primary tumor volume was significantly lower in KD1- or KD2-injected mice, suggesting that Rab40b plays a role in regulating primary tumor growth." (PMID 27789576, 2016). "Another possible explanation for the reduced tumor size in the Rab40b KD mice could be the lack of invasion and dispersal of cells within the tumor." (PMID 27789576, 2016). "Given that Rab40b knockdown does not appear to directly affect cell proliferation in vitro, we tested whether proliferation and/or apoptosis were altered within the primary tumor." (PMID 27789576, 2016). "Upon depletion of Rab40b, the lack of MMP2 and MMP9 targeting could lead to reduced angiogenesis, thus inhibiting tumor growth." (PMID 27789576, 2016).
RAB40B also shares sentences with these, for which no sentence is quoted: hepatocellular carcinoma (1 paper); infection (1).